TEX52 (testis expressed 52)
Tractability: No criterion of Open Targets' tractability assessment is met for any kind of drug.
Gene: Protein-coding gene on chromosome 12 (2,849,046 to 2,857,039, reverse strand). Ensembl gene ENSG00000283297.
Subcellular location (Human Protein Atlas): Nucleoplasm; Cytosol
Genetic constraint (gnomAD): Loss-of-function variants: 21 observed, 15.92 expected, observed/expected ratio (o/e) 1.32, 90% interval 0.93 to 1.82. The upper end of that interval is the gene's LOEUF score, 1.82, which puts it in group 6 of 6, group 1 being the genes least tolerant of losing a copy. Missense variants: 372 observed, 353 expected, observed/expected ratio (o/e) 1.05, 90% interval 0.97 to 1.15. Synonymous variants: 155 observed, 138.46 expected, observed/expected ratio (o/e) 1.12, 90% interval 0.98 to 1.28.
Homologues: Orthologues: chimpanzee TEX52 (99% identical), macaque TEX52 (96% identical), pig TEX52 (75% identical), dog TEX52 (72% identical), rabbit TEX52 (70% identical), mouse Tex52 (67% identical), rat Tex52 (64% identical), guinea pig TEX52 (63% identical).